SOCS2 (suppressor of cytokine signaling 2)
Diseases named in the same sentence as SOCS2 in open-access papers (continued):
Sharing a sentence is not in itself a finding about the gene and the disease.
cancer (77 papers, 2007 to 2026). A tumor composed of atypical neoplastic, often pleomorphic cells that invade other tissues. "In cancer patients, SOCS2 expression is associated with both a better and worse prognosis depending on the cancer type." (PMID 34857742, 2021). "The researchers also identified a gene commonly mutated in cancer cells that can drive overproduction of SOCS-2." (PMID 29622769, 2018). "It has been identified as possibly protective against many cancers, although some cancers are associated with elevated SOCS-2 levels." (PMID 29622769, 2018). "A number of aging- and cancer-associated genes were observed among the 420 predicted bowhead-minke orthologs with dN/dS exceeding 1, including suppressor of cytokine signaling 2 (SOCS2), aprataxin (APTX), noggin (NOG), and leptin (LEP)." (PMID 25565328, 2015). "Furthermore, it is also worth noting that reduced expression of SOCS2 has been associated with increased cancer risk, which may be a consequence of increased GH signaling." (PMID 29343614, 2018). "Genes often found to be epigenetically silenced or with low expression levels in ovarian or other cancers (Adora1, Bmp3, Ccl6, Ephx2, Lefty2, Pf4, Socs2) were downregulated by MOSE-LTICv in the OFB." (PMID 38264656, 2023). "Because mobility is a significant feature of cancer cells, studies on the effects of SOCS2 on cancer cell mobility phenotypes are important." (PMID 35037826, 2022). "Western blot assays confirmed that si-SOCS2 and miR-3648 inhibitors were successfully transfected into the cancer cells." (PMID 35037826, 2022). "SOCS2 was identified as a key direct target gene of miR-877-3p in GC, where miR-877-3p suppressed the expression of SOCS2 and promoted cancer cell stemness and chemoresistance subsequently by activating Jak2/Stat3 signaling." (PMID 35600882, 2022). "SOCS2 suppresses the cytokine-induced signaling transduction and its downregulation is observed in many cancers." (PMID 34054537, 2021). "SOCS2 clearly has many diverse roles in biological processes that are important for cancer, autoimmunity, and other inflammatory diseases." (PMID 34857742, 2021). "SOCS2 was mainly expressed in liver sinusoidal endothelial cells (LSECs) and lymphatic vascular endothelial cells (LVECs), while moderately expressed in carcinoma cells." (PMID 34726341, 2021). "Mechanistically speaking, METTL3 targets the suppressor of cytokine signaling 2 (SOCS2), a cancer suppressor, and increases the m6A level of it." (PMID 32612834, 2020). "These evidences highlight the potential in targeting SOCS2 for drug discovery for inflammation and cancer biology." (PMID 31182716, 2019). "SOCS2, one of the members of the SOCS family, is implicated in disorders of the immune system, central nervous system and cancer, and is thus emerging as a promising therapeutic target 22–25." (PMID 31182716, 2019). "Our data support further investigation of SOCS2/3 as signalling effectors, prognostic indicators and potential therapeutic targets in cancers with JAK2 rearrangements." (PMID 23372669, 2013). "Several studies indicate that in addition to its actions on GHR signalling, SOCS2 also has important actions in neuron development, the regulation of metabolism, mammary gland development and cancer as well as the immune response." (PMID 21980433, 2011). "SOCS2 may be involved in the apoptosis or necrosis of cancer cells, which may eventually influence the progression of HCC." (PMID 39307915, 2024). "A pan‐cancer analysis revealed that SOCS2 levels were down‐regulated in numerous cancers." (PMID 37246269, 2023). "In addition to proliferation, we also investigated the effect of SOCS2 on the miR-3648-mediated invasive and migratory abilities of the cancer cells." (PMID 35037826, 2022). "SOCS2 was also proved as a therapeutic resistance-related gene for cancers." (PMID 35812443, 2022).
cancer (continued). "However, it is the emerging relationship between SOCS2, immunity, and cancer that has generated interest in understanding the role of SOCS2 in cancer etiology." (PMID 34857742, 2021). "SOCS2 proteins are important negative regulators of cytokine signal transduction, and their inhibition may be an effective therapeutic strategy for cancer treatment." (PMID 32211443, 2020). "Suppressor Of Cytokine Signalling 2 (SOCS2) is transcriptionally activated by JAK-STAT signalling and encodes a negative feedback regulator of this pathway, which is aberrantly activated in many cancers including AML22." (PMID 31235852, 2019). "Several studies illustrate the impact of SOCS2 on certain cancers." (PMID 29559623, 2018). "Therefore, if GH treatment or novel therapies to target the SOCS2 protein are to be considered as bone-protective agents in children and adults with IBD, then the potential cancer risk has to be carefully considered." (PMID 29343614, 2018). "Since IGF1 signalling confers the EMT to several types of cancer cells, we further examined whether SOCS2 is involved in the IGF1-induced EMT process of lung adenocarcinoma cells." (PMID 29559623, 2018). "Finally, within the list of upregulated genes in the UCHL1 KD we also found several cancer-associated genes such as SERPINB4, FGF21, NUPR1, SBSN, GDF1, HMOX1, or SOCS2, which suggested the activation of potential compensatory mechanisms in these KDs cells." (PMID 28472177, 2017). "Since SOCS2 deficiency could lead to an elevated NDR1 levels, we wanted to see how an “over-expressing” NDR1 protein itself would impinge on the tumorigenic properties of cancer cells." (PMID 28216640, 2017). "For instance, YTHDF2 modulates the m6A methylation of OCT4 mRNA to promote the cancer stem cell phenotype and cancer metastasis; while METTL3 promotes HCC progression through an m6A-YTHDF2-dependent post-transcriptional silencing of SOCS2." (PMID 39799112, 2025). "Lanatoside C, a cardiac glycoside, has been shown to induce apoptosis in cancer cells by suppressing the Janus kinase (JAK)/signal transducer and activator of transcription (STAT)/cytokine signaling (SOCS) (JAK2/STAT6/SOCS2) pathway." (PMID 38527038, 2024). "M6A‐related genes such as BRD4, MYC, SOCS2, and EGFR are frequently involved in the progression of cancers including LUAD." (PMID 39323079, 2024). "The suppressor of cytokine signaling 2 (SOCS2) promotes ferroptosis and radiosensitization in cancer by enhancing the ubiquitination of SLC7A11." (PMID 37714846, 2023). "In detail, EGR1, TPP1, and SOCS2 conferred drug resistance, while RRM2 and C11orf54 exhibited drug sensitivity in pan-cancers." (PMID 35812443, 2022). "Further analysis reveal that EGR1, TPP1, and SOCS2 confer drug resistance, while RRM2 and C11orf54 exhibit drug sensitivity in pan-cancers." (PMID 35812443, 2022). "Thus, our results showed that miR-3648 might promote cancer by downregulating SOCS2 expression." (PMID 35037826, 2022). "For instance, YTHDF2 recognizes the methylation of suppressor of cytokine signaling 2 (SOCS2) and arrestin domain-containing protein 4 (ARRDC4) and induces their mRNA degradation thus enhances metastasis and dissemination of cancer cells." (PMID 35974338, 2022). "SOCS2, which is a member of the suppressor of cytokine signaling (SOCS) family, can repress the cytokine-induced signaling transduction, thus inhibiting cancer progression." (PMID 35864511, 2022). "Conversely, SOCS2 and DNASE1L3 were down‐regulated in most cancer tissues compared to normal tissues." (PMID 34726341, 2021). "SOCS2 is a member of the suppressor of cytokine signaling (SOCS) family and represses the cytokine-induced signaling transduction, thus inhibiting cancer progression." (PMID 34054537, 2021). "Among LS samples, NTSR1, SOCS2, and SOCS1 showed tentatively increased methylation frequencies in carcinomas compared to normal mucosae, but only NTSR1 remained significant after adjustment for multiple testing (p = 0.037)." (PMID 34680073, 2021).
cancer (continued). "We found that seven genes (ADPRH, IL1R1, KSR1, SOCS2, JAK1, NFAT5, and SSH1) were more highly expressed in the lower-TMB subtype than in the higher-TMB subtype of more than 10 cancer types." (PMID 30634925, 2019). "On the other hand, SOCS2 and IQGAP2 relay interactions with factors that are released by immune cells, including various types of cytokines, potentially allowing for cancer cells to be aware of the immune environment." (PMID 31480259, 2019). "Suppressor of cytokine signaling 2 (SOCS2), which is a member of the SOCS protein family, binds with growth factor receptor (GHR) to repress growth factor-induced signal transduction, thus inhibiting cancer progression." (PMID 35757505, 2022). "Moreover, the inhibitory effects of anti-miR-500a-3p on cancer stem cell phenotypes and activity of STAT3 signaling were reversed by silencing SOCS2, SOCS4 and PTPN11 in miR-500a-3p-downexpressing cells, respectively." (PMID 28750679, 2017). "Likewise, we found a number of genes whose expression follows this pattern: late-stage cancers < early-stage cancers < normal tissue, such as ADHFE1, LOC653501, NT5DC1, RSBN1, SOCS2 and TAPT1 in five cancer types." (PMID 28427185, 2017). "Clinical research has shown that SOCS2 is an independent predictor for good prognosis, negative lymph nodes and has increased expression in less malignant tumors." (PMID 20003295, 2009). "We also identified the top 1 GEAR in individual cancer types, such as TLL1 (BLCA), PGK1 (BRCA), RFXANK (CESC), DPP7 (COAD), VWA8 (KIRC), SCMH1 (LGG), HILPDA (LIHC), TLE1 (LUAD), CD151 (LUSC), ANKRD13A (OV), SOCS2 (PAAD), DRG2 (PRAD), ADAMTS6 (STAD), PSMB8 (THCA), ASS1 (UCEC)." (PMID 41404730, 2025). "To confirm our hypothesis that miR-3648 mediates its oncogenic effects by negatively regulating SOCS2, we transfected cancer cells with a miR-3648 inhibitor with or without si-SOCS2 and performed a series of experiments." (PMID 35037826, 2022). "KEGG pathway analysis further highlighted the role of S6K1 in cancer progression, in which the depletion of S6K1 could re-express a group of tumor suppressor genes including RASSF5, RASSF6, STAT1, CEACAM1, BNIP3L and SOCS2." (PMID 32201535, 2020). "Since SOCS2 elevation is often considered to be the consequence of STAT3 activation and acts a negative feedback mechanism, SOCS2 might highly express in those STAT hyper-activated cases, of which might originally be greater malignant tumor." (PMID 31801484, 2019). "Our findings further reveal miR-500a-3p promotes the cancer stem cell characteristics via targeting multiple negative regulators of JAK/STAT3 signaling pathway, including SOCS2, SOCS4 and PTPN11, leading to constitutive activation of STAT3 signaling." (PMID 28750679, 2017).
infection (35 papers, 2008 to 2025). The state of being infected such as from the introduction of a foreign agent such as serum, vaccine, antigenic substance or organism. "A recent study has identified a point mutation in SOCS2 about an increased inflammatory response, and a higher prevalence of infections by Staphyloccoci." (PMID 39185412, 2024). "In the intermediate acute phase of infection, Zi reduced thenumber of innate and adaptive inflammatory cells, increased the levelof SOCS2 expression in the heart associated with lower inflammation,and improved cardiac function." (PMID 39609255, 2024). "Along with infection with S. aureus, the initiation of the inflammatory reaction was similar between the two SOCS2 variants." (PMID 39185412, 2024). "Identification of a loss-of-function (LOF) mutation in SOCS2 provides a good opportunity to study the role of SOCS2 in the context of infection, using a more physiological model than with knockout mice." (PMID 39185412, 2024). "The CT genotype of rs2057178 was also associated with decreased expression levels of infection-related gene, suppressor of cytokine signaling 2 (SOCS2), and increased expression levels of v-maf avian musculoaponeurotic fibrosarcoma oncogene homolog B (MAFB)." (PMID 27035414, 2016). "In addition, studies using Suppressor of cytokine signaling 2 (SOCS2) deficient mice (C57BL/6 background) showed that low Treg levels protected from infection with the Y strain, while increased immunopathology." (PMID 29545782, 2018). "On the other hand, enhancing the JAK-STAT signaling activation by silencing the inhibitor SOCS2 transformed normal infection into acute infection." (PMID 39819453, 2025). "The action of acetylsalicylic acid, an anti-inflammatory drug, was shown to be dependent on SOCS2, confirming its role in both the immune response to infection and the regulation of inflammatory processes." (PMID 39185412, 2024). "In various infection models like Toxoplasma gondii, Trypanosoma cruzi, and Plasmodium berghei Anka, Socs2 has been recognized as a modulator of innate and adaptive immune responses." (PMID 39062636, 2024). "SOCS2 has also been reported to play important roles in key adaptive phenotypes in sheep, including general immune response following infection and resistance to gastrointestinal nematode (Haemonchus contortus)." (PMID 34349777, 2021). "For example, suppressors of cytokine signalling (SOCSs) proteins SOCS3 and SOCS2 belonging to important family of inflammatory response regulators were shown to augment the infection with M. tuberculosis and S. enterica." (PMID 32070192, 2020). "After 48 h infection, the SOCS2 protein level increased in the Ad-SOCS2 group while decreased in the sh-SOCS2 group compared with the control group (P < 0.05)." (PMID 32733634, 2020). "SOCS2 protein has been recognized to modulate the innate and adaptive immune response in different experimental models of infection, including models of Toxoplasma gondii, Trypanosoma cruzi, and Plasmodium berghei Anka infection." (PMID 31949423, 2019). "Expression of Csf1-lnc and Socs2-lnc was significantly reduced during infection with the ROP16 deletion mutant (RH∆16) compared to RH." (PMID 30301916, 2018). "Ad-SOCS2 infection alleviated STZ-induced renal injury and pathological changes and inhibited STZ-induced IL-6, IL-1β and MCP-1 generation and activation of the TLR4/NF-κB pathway in DN rats." (PMID 29207635, 2017). "Treatment with ASA early in infection not only ablated TNF-α release from spleen but also increased SOCS-2 and reduced TRAF6 expression." (PMID 21347238, 2011). "Starting from the early infection stage (12 hpi), SOCS2 and SOCS5 show marked increasing trend in Asx and this trend persists throughout the entire infection period." (PMID 21901105, 2011). "In general, DCs were more responsive than Mφs to infection, with more genes induced, such as SOCS2, ISG20, TRAF5 and IRF4." (PMID 18167562, 2008).
infection (continued). "To conclude, our results show that the SOCS2 protein plays an important role in the immune response by controlling inflammatory cytokine production and reducing cell infiltration at the early stage of infection." (PMID 39185412, 2024). "Reduction in the inflammation found in SOCS2−/− mice using this EAE model is consistent with results from our group that showed reduced inflammation in the brain of P. berghei Anka-infected mice at the early stage of the infection and in the T. cruzi-infected heart of SOCS2−/− mice." (PMID 31949423, 2019). "Recently, SOCS2 has been recognized as a modulator of the immune system in different experimental models, playing several immune and oxidative stress regulatory functions, notably during infections." (PMID 30723477, 2018). "Moreover, DN rats infected with Ad-SOCS2 presented a decrease of renal injury as demonstrated by reduced extracellular matrix deposition with respect to that with Ad-GFP infection." (PMID 29207635, 2017). "However, these also indicate that SOCS2 expression is mainly induced in the late phase of infection in an IFN-mediated manner." (PMID 22291912, 2012). "Another study showed that SOCS2 might be involved in the regulation of the immune response upon infection." (PMID 19779605, 2009). "Similarly in the LCMV-infected primate, IRS1 expression is decreased and expression of IRS2 is moderate, but SOCS2 is up-regulated (7.2-fold) at the pre-viremic stage of infection." (PMID 19216742, 2009). "Additionally, to isolate effects of live infection from other potential sources of gene regulation (such as the presence of dead parasites or soluble parasite protein), we examined expression of Socs2-lnc after addition of live, dead, and soluble tachyzoite antigen (STAg)." (PMID 30301916, 2018). "To further substantiate the biological relevance of LXA4/SOCS2/AhR pathway in controlling pro-inflammatory response during infection with T. gondii, we perform histopathological analysis of the brain and liver tissues obtained from WT, SOCS2-KO and AhRd mice at 30 days after infection." (PMID 22693634, 2012). "Following infection, the amount of dietary CHMM was shown to significantly downregulate (P < 0.05) the level of SOCS2, and the lowest expression observed in the 30 g/kg group." (PMID 38694480, 2024). "The expression of the SOCS-2 and SOCS-6 genes increased in B. mori after infection by viral, bacterial, and fungal pathogens." (PMID 36142300, 2022). "Here, we show that human DCs rapidly upregulate SOCS3 expression after infection with wild-type H. pylori P12, whereas the induction of SOCS1 and SOCS2 expression is observed only at later time points." (PMID 33023610, 2020). "Our data indicate a specific and strong upregulation of SOCS3 after 1 h of infection, while SOCS1 and SOCS2 displayed delayed kinetics." (PMID 33023610, 2020). "Our data reveal that SOCS3 mRNA was already induced within 1 h of infection, whereas SOCS1 and SOCS2 expression was delayed and detectable only after 8 h." (PMID 33023610, 2020). "In contrast, silencing of SOCS1 and SOCS2, respectively, did not significantly alter the DC phenotype upon infection." (PMID 33023610, 2020). "Unlike HSV-1 infection, infection with BHV-5 exacerbates meningoencephalitis in SOCS2-knockout mice compared with wild type animals, suggesting a protective role during intracranial BHV-5 infection." (PMID 31031749, 2019). "In the absence of lipoxins or SOCS2, infection with T. gondii is lethal due to aberrant uncontrolled inflammation." (PMID 22693634, 2012). "Most deaths of the SOCS2-dsRNA treated shrimp occurred within 4–8 hpi, earlier than those of the GFP-dsRNA treated control, indicating that enhancing the activation of JAK-STAT signaling could transform normal infection into acute infection in shrimp." (PMID 39819453, 2025).
infection (continued). "SOCS2 mRNA and protein were induced by lipoxin (LXA4), an eicosanoid mediator with potent anti-inflammatory properties in DCs, and SOCS2 knock-out mice showed decreased microbial proliferation, leukocyte infiltration, production of pro-inflammatory cytokines, and a high mortality upon infection." (PMID 19779605, 2009). "Nevertheless, during infection with the PTG strain, we identified two loci, Ifi44-lnc and Socs2, that were not expressed in the microarray but did appear to be regulated in the qRT-PCR." (PMID 30301916, 2018). "Suppressor of cytokine signaling 2 (SOCS2), a member of the SOCS protein family, is a negative regulator of biological processes mediated by various cytokines, such as metabolism, skeletal muscle development, and the response to infection." (PMID 30930940, 2019).
bacterial infection (3 papers, 2015 to 2024). "Here, we show that SOCS2 plays a more important role in the regulation of the response to bacterial infection and inflammation than initially thought." (PMID 39185412, 2024). "The role of SOCS2 has been little investigated during bacterial infection." (PMID 39185412, 2024).